WEE1 (WEE1 G2 checkpoint kinase)
Diseases named in the same sentence as WEE1 in open-access papers (continued):
Sharing a sentence is not in itself a finding about the gene and the disease.
tumor (continued). "It is a function which is likely to be important in tumour expansion and progression and therefore likely to be important in the clinical actions of WEE1 inhibitors such as AZD1775." (PMID 28178688, 2017). "In the 5637 xenografts, the reduction in the tumour volumes corresponded to an increase in Wee1 expression, CDC2 (Thr14/Tyr15) phosphorylation and the decrease in BubR1 expression, as determined by Western blotting." (PMID 27878946, 2017). "The WEE1 inhibitor, AZD1775, also known as MK-1775 potently radiosensitizes human tumor cells, suggesting that these tumors rely on WEE1 kinase activity for chromatin integrity." (PMID 29290954, 2017). "The implication is that WEE1 inhibitors are likely to reduce the extent of tumour vascularisation independently of effects on tumour cells." (PMID 28178688, 2017). "In the 5637 xenograft model, the reduction of the tumour weights corresponded to the increase in Wee1 expression, CDC2 (Thr14/Tyr15) phosphorylation and the reduction in PLK1 expression." (PMID 27878946, 2017). "The anti-tumor activity of the combination of Chk1 and wee1 inhibitors has been tested in several previous reports, generally indicating that the combination produces a synergistic effect on tumor cell proliferation or viability." (PMID 27690219, 2016). "Several clinically available chemotherapeutic drugs (carboplatin, paclitaxel, and etoposide) and drugs at the developmental stage (Wee-1 and heat shock protein 90 inhibitors) show a sensitizing effect on tumor cells treated with carbon ions." (PMID 27376029, 2016). "For instance, recent studies also showed that combined inhibition of checkpoint kinase 1 (CHK1), another inducer of G2/M phase arrest, and WEE1 increased therapeutic efficacy and reduced tumor growth." (PMID 27616351, 2016). "We have observed that Wee1 inhibition potentiates Wip1-dependent tumor sensitization effect by reducing levels of Hipk2 kinase, a negative regulator of Wip1 pathway." (PMID 27077811, 2016). "These include a number of genome maintenance genes such as MCM subunits, Plk1, Wee1, Bub1 or cyclins that are also downregulated by the vGPCR and miR-34a in our tumor model." (PMID 26871287, 2016). "The Wee1 inhibitor, MK-1775, sensitizes tumor cells towards gemcitabine with particular efficiency, even when compared to inhibitors of ATR and Chk1." (PMID 25965828, 2015). "Given that NPC cells were significantly more sensitive than nasopharyngeal epithelial cells to WEE1i, we also evaluated the effects of WEE1 inhibition on NPC growth in animal tumor models." (PMID 26025928, 2015). "Tumors from control or EC-8042-treated mice removed 6h after the last treatment showed that tumoral samples from mice treated with the drug had increased levels of Wee1, pCDK1-Y15, p27, Cyclin A and Cyclin B." (PMID 26439989, 2015). "By inhibiting Wee1, small molecular inhibitors of Wee1 potentiate the activity of cytotoxic agents and thus act to sensitize the tumor cell to the cytotoxic agent." (PMID 26125596, 2015). "To assess the role of Wee1 in tumor cell proliferation we performed small interfering RNA (siRNA) experiments in a panel of diverse cell lines derived from various tissue origins." (PMID 24927813, 2014). "Several studies have demonstrated that pharmacological inhibition of Wee1 by the small molecule kinase inhibitor MK-1775 leads to removal of CDC2 phosphorylation at Tyr15 in tumor cells." (PMID 23520471, 2013).
tumor (continued). "MiR-15a has been shown to be tumor suppressive in other systems, primarily through regulation of a variety of cell cycle targets, including Wee1 and multiple cyclins." (PMID 23638178, 2013). "Based on distribution, positive immunoreactivity in ≥10% of the tumor cells was used as cut-off to discriminate between high and low Wee1 expression." (PMID 22719872, 2012). "We demonstrate here that combination of a CHK1 inhibitor, MK-8776, and a WEE1 inhibitor, MK-1775, results in synergistic inhibition of cell proliferation in several human tumor cell lines." (PMID 23148684, 2012). "Consistent with the PD data, we demonstrate that the combination of CHK1 and WEE1 inhibitors leads to greater-than-additive tumor growth inhibition in two human tumor xenograft models." (PMID 23148684, 2012). "It is believed that such destabilization of client proteins (like raf, Src, Lck, Wee1, Mek, Cdk4, Src, Ck2, Akt, ErbB2 etc.)is responsible for the anti-mitotic and anti-tumor activity of the drug." (PMID 22361388, 2012). "WEE1 expression in OS was investigated by gene-expression data analysis and immunohistochemistry of tumor samples." (PMID 21529352, 2011). "The anti-tumor activity of WEE1 inhibition in combination with DNA damaging treatments has been demonstrated in vitro as well as in vivo models for different malignancies." (PMID 21529352, 2011). "This allows investigators to precisely correlate the changes in the expression of the Wee1 gene signature and anti-tumor efficacy of the Wee1 inhibitor." (PMID 19500427, 2009). "The availability of the Wee1 gene signature in skin samples offers an advantage due to the difficulty of obtaining tumor biopsies from patients." (PMID 19500427, 2009). "WEE1 inhibitors can also be combined with PARPis to enhance tumour cell cytotoxicity." (PMID 41537447, 2026). "Moreover, we showed the anti‐tumour effects of the specific Wee1 inhibitor AZD1775 as a single agent in ACC cells." (PMID 39528354, 2025). "Tackling these resistance mechanisms may require combination approaches, such as pairing PARP inhibitors with ATR or WEE1 inhibitors to prevent replication stress recovery, or with checkpoint inhibitors to enhance tumor immunogenicity." (PMID 40842586, 2025). "Therefore, essential protein kinases involved in orchestrating this arrest, namely Chk1 and Wee1, have been suggested as targets to enhance the sensitivity of tumour cells to radiotherapy." (PMID 39994186, 2025). "Further studies linking these biomarkers with high WEE1 inhibitor sensitivity could extend the use of these targeted agents to other tumor types." (PMID 39820427, 2025). "Due to the strong synergistic effects observed between WEE1 inhibitors and G12C inhibitors in in vitro cell models, we further validated the efficacy and safety of the combination strategy involving WEE1i and G12Ci in xenograft tumor models in vivo." (PMID 40885709, 2025).
tumor (continued). "Moreover, SHCBP1 inhibition in tumour cells abrogated the G2–M checkpoint by downregulating the WEE1 kinase to break the balance between genotoxic stress and the cell cycle arrest and repair system, resulting in further tumour growth inhibition." (PMID 38365687, 2024). "WEE1 plays a pivotal role in tumor progression and is a promising therapeutic target." (PMID 38231277, 2024). "Whilst WEE1 inhibition may be a useful means of treating tumours with CCNE1 overexpression, identifying novel synthetic lethality targets through genome wide screens may highlight alternative strategies." (PMID 39135999, 2024). "Thus, WEE1 kinase inhibition with adavosertib has been shown to induce tumor regression in CIC::DUX4 tumor xenograft models." (PMID 38882060, 2024). "More systematic studies comparing the impact of different radiation sources in well-defined tumour (and normal) models are therefore needed to understand the potential for Chk1 or Wee1 inhibitors to be utilised in order to optimise tumour radiosensitisation to the various radiation modalities." (PMID 39272874, 2024). "The review highlights the intricate involvement of WEE1 in tumor progression and drug resistance." (PMID 38231277, 2024). "Finally, it is still unclear which specific tumours will significantly benefit from Chk1/Wee1 inhibition in combination with radiotherapy in the clinic." (PMID 39272874, 2024). "Furthermore, in vivo assessments demonstrated substantial tumor growth suppression due to WEE1 inhibitors." (PMID 38169513, 2024). "In addition, we found that the premature M-phase entry in tumour cells after SHCBP1 knockdown was due to WEE1 kinase downregulation, which resulted in decreased CDK1 phosphorylation at the Tyr15 residue." (PMID 38365687, 2024). "WEE1 inhibition has exhibited significant potential in tumor treatment." (PMID 38231277, 2024). "Nevertheless, in patients with HNC, the Wee1 inhibitor adavosertib has shown favorable safety, tumor response, and survival as an adjuvant to platinum chemoradiotherapy as well as high tolerability and overall responses when combined with cisplatin and docetaxel." (PMID 38612819, 2024). "However, the effects of WEE1 inhibitors on cell proliferation, the cell cycle, and the tumor immune microenvironment in CRC are not yet fully understood." (PMID 39335109, 2024). "An initial phase II clinical trial evaluating the anti-tumor effects of a WEE1 inhibitor in recurrent serous endometrial carcinoma found that recurrence-free survival at 6 months achieved 47.1%, suggesting the potential therapeutic promise of WEE1 inhibitors in endometrial cancer." (PMID 38169513, 2024). "Additionally, we investigated the effects of the WEE1 inhibitor on the tumor immune microenvironment using an orthotopic transplantation mouse model." (PMID 39335109, 2024). "However, as a protein kinase in the nucleus, the regulatory role of Wee1 in tumor cells is not limited to the regulation of cell cycle checkpoints." (PMID 37102239, 2023). "Inhibition of WEE1 or CHK1 suppressed tumor growth and metastasis in vivo." (PMID 37987002, 2023). "Indeed, we show that STING agonism synergised with PARP and WEE1 inhibition which markedly increased proinflammatory anti-tumour immunity in the AT3 tumours resulting in tumour regression and prolonged survival." (PMID 37582853, 2023).
tumor (continued). "Recent data support the notion that the effectiveness of Wee1 inhibitors relies on an interplay between replication stress and cell cycle checkpoint failure, as evidenced through combined inhibition of PARP and Wee1, which appears to confer tumor-specific radiosensitization of HPV(+) HNSCC cells." (PMID 36769087, 2023). "Notably, both cIAP and WEE1 inhibitor drug classes are modulators of the TNFα-NFκB pathway, which regulates proliferation, cell death, and tumor promoting inflammation in HNSCC." (PMID 36831373, 2023). "Moreover, WEE1 inhibition can boost anti-tumor immunity by activating ERV and the dsRNA pathway and strengthen sensitivity to immune checkpoint blockade." (PMID 37051542, 2023). "We hypothesise that combined PARP and WEE1 inhibition might likewise activate STING-dependent anti-tumour immune response in BRCA wild-type TNBC." (PMID 37582853, 2023). "We identify histone deacetylase and/or WEE1 inhibitors as potential therapeutic vulnerabilities in these tumors, which might also restore tumor immunogenicity and potentially enhance the effects of immunotherapy." (PMID 38036539, 2023). "The results showed that the RRCPP/si WEE1 complex loaded with WEE1 siRNA drugs could significantly inhibit tumour growth in melanoma cancer models with high stability and feasibility." (PMID 35593206, 2022). "Immunohistochemical (IHC) analysis of NCC_CDS1_X1_C1 tumor explants further validated that WEE1 inhibition increased DNA damage and enhanced apoptosis, as demonstrated by increased γH2AX and cleaved caspase-3 expression in mice treated with adavosertib compared with vehicle control." (PMID 35315355, 2022). "Furthermore, patients with high levels of CDK1 and WEE1 exhibit more aggressive TNBC tumours (classified as grade 3)." (PMID 34646365, 2021). "Starting from the core structure of polyphenols, Lamoral-Theys’ group designed and synthesized several di- and trivanillate compounds, with some of them presenting WEE1 inhibitory and anti-tumor activities, probably due to their inhibitory activity against the Aurora A/B/C responsible." (PMID 34639030, 2021). "Finally, in the animal model with a conditional expression of Wee1 in the mammary gland, they demonstrated that Wee1 is indispensable for maintaining genomic stability and it acts as a haploid tumor suppressor since a mutant mammary gland develops tumors." (PMID 34639030, 2021). "As shown in other tumor types, inhibitors targeting molecules such as ATR, Wee1 and Chk1, which induce replication-associated DNA damage and potentially cGAS/STING pathway activation through subsequent cytosolic DNA fragments in HNSCC, are promising candidates for combination treatments in HNSCC." (PMID 34204886, 2021). "Moreover, this study demonstrated that tumor cell lines that overexpress Wee1 are more sensitive to Wee1 inhibition by siRNA, leading to abrogation of the G2/M checkpoint and consequent tumor cell death via apoptosis." (PMID 34639030, 2021). "Previous studies have found that miRNAs could regulate the malignant phenotypes of tumor cells via targeting WEE1." (PMID 33986660, 2021). "The overexpression of miR‐125b‐2‐3p slowed tumor growth and increased drug sensitivity; moreover, knocking down WEE1 further slowed growth and promoted drug sensitivity, finally when miR‐125b‐2‐3p was overexpressed, lncRNA XIST was knocked down and WEE1 knocked down simultaneously." (PMID 33666372, 2021).
tumor (continued). "Similarly, in nude mice, we confirmed that AKT/Wee1/CDK1 axis was also involved in tumor growth during exposure to high iodine." (PMID 33796458, 2021). "Knockdown of Oct4 A isoform reduced self-renewal capacity in HNSCC and led to partial tumor cell radiosensitization caused by transcriptional downregulation of the cell cycle checkpoint kinases CHK1 and WEE1 and homologous recombination (HR) repair genes PSMC3IP and RAD54L." (PMID 34079088, 2021). "From this perspective, Wee1 inhibition might increase the effectiveness of DNA-damaging treatments, such as radiotherapy, forcing tumor cells and CSCs to enter into mitosis, even with damaged DNA, leading to mitotic catastrophe and subsequent cell death." (PMID 34639030, 2021). "Furthermore, it has been suggested that with optimised dose scheduling, combined PARP and WEE1 or ATR inhibition can enhance tumour killing with minimal systemic toxicity, owing to higher basal levels of replication stress in malignant versus normal tissue." (PMID 32444694, 2020). "Combination of DN052 and WEE1 inhibitor showed potential synergy in suppressing tumor growth." (PMID 35006413, 2020). "Additionally, qRT‐PCR revealed that WEE1 expression was markedly enhanced in tumor tissues of NBL patients (P < .001)." (PMID 32886453, 2020). "Taken together, this study reports that replication stress induced by overexpression of Cyclin E1 and Cdc25A results in the formation of lagging chromosomes and chromatin bridges, which is further exacerbated by inhibition of ATR or WEE1 kinases, and results in exacerbated tumor cell killing." (PMID 33028815, 2020). "With the current development of BH3 mimetics, WEE1 inhibition would be an excellent candidate for dose reduction combination therapy in treatment-naïve patients, or could be applied as a BH3 mimetic sensitizer in WEE1 inhibitor-resistant tumours." (PMID 31703356, 2019). "miR-410-3p upregulated the level of Wee1 as tumor suppressor miR in GH3 cells." (PMID 31165412, 2019). "We hypothesized that WEE1 kinase inhibition could sensitize tumor cells to granzyme B-dependent NK killing." (PMID 29925431, 2018). "Importantly, immunohistochemistry analyses of these tumours showed decreased levels of Wee1 expression in vivo." (PMID 28145098, 2017). "Taken together with other recently published reports, our results add another level of evidence that the efficacy of WEE1 inhibition is influenced by the DNA repair status of a cell and may also be dependent on the tumor type and model evaluated." (PMID 27616351, 2016). "The non redundant roles are consistent with the in vitro and in vivo data collected on the synergistic activity of combining Chk1 and Wee1 inhibitors in solid tumors which was shown to be specific for tumor cells, thus enhancing the therapeutic potential of this combination." (PMID 25428911, 2015). "Moreover, high expression of Wee1 in the cytoplasm significantly correlated with poor tumor differentiation (P = 0.007)." (PMID 23767999, 2013). "Wee1 expression correlates with clinical parameters- and markers of tumor progression." (PMID 22719872, 2012). "Moreover, network analysis suggests another, tumor-specific module of cell cycle regulators formed by p107, p130, p15INK4b, and Wee1." (PMID 21464922, 2011). "Furthermore, the level of phosphorylation at Y15 is correlated with the anti-tumor efficacy of the Wee1 inhibitor." (PMID 19500427, 2009). "Accordingly, loss of WEE1 kinase activity and its destruction is a requirement for entry into mitosis, suggesting that WEE1 activity may actually limit tumour cell growth." (PMID 19357772, 2009). "Consequently, these tumours are reliant on the G2/M cell cycle checkpoint driven by Chk1 and Wee1." (PMID 39994186, 2025).